ANKS6 (ankyrin repeat and sterile alpha motif domain containing 6)
Description:
Required for renal function.
Synonyms: ANKRD14; PKDR1; SAMD6; FLJ36928; NPHP16
Tractability: PROTAC: ubiquitination databases record sites on it.
Gene: Protein-coding gene on chromosome 9 (98,731,329 to 98,796,965, reverse strand). Ensembl gene ENSG00000165138.
Subcellular location: Cell projection, cilium; Cytoplasm
Subcellular location (Human Protein Atlas): Nucleoli fibrillar center; Primary cilium; Cytosol
Gene Ontology:
Molecular function: protein binding
Cellular component: cytoplasm; cilium
Genetic constraint (gnomAD): Loss-of-function variants: 43 observed, 63.84 expected, observed/expected ratio (o/e) 0.67, 90% interval 0.53 to 0.87. The upper end of that interval is the gene's LOEUF score, 0.87, which puts it in group 3 of 6, group 1 being the genes least tolerant of losing a copy. Missense variants: 1,119 observed, 1,051.1 expected, observed/expected ratio (o/e) 1.06, 90% interval 1.01 to 1.12. Synonymous variants: 473 observed, 450.71 expected, observed/expected ratio (o/e) 1.05, 90% interval 0.97 to 1.13.
Gene-disease validity (ClinGen):
ClinGen rates the evidence that ANKS6 causes each of these diseases.
nephronophthisis 16 (autosomal recessive): Definitive.
Homologues: Orthologues: chimpanzee ANKS6 (99% identical), macaque ANKS6 (98% identical), pig ANKS6 (94% identical), dog ANKS6 (92% identical), mouse Anks6 (86% identical), rat Anks6 (86% identical), guinea pig ANKS6 (73% identical), tropical clawed frog anks6 (64% identical), rabbit ANKS6 (58% identical). Paralogues in human: BICC1 (20% identical), HDLBP (14% identical).
Diseases named in the same sentence as ANKS6 in open-access papers:
ANKS6 is named in the same sentence as 23 diseases in open-access papers, as found by Europe PMC text mining. Sharing a sentence is not in itself a finding about the gene and the disease. The quoted sentences say what the papers report.
cystic kidney disease (9 papers, 2014 to 2024). A congenital or acquired kidney disorder characterized by the presence of renal cysts. "The phenotype is the result of a missense mutation in Anks6 that encodes for SamCystin, and results in renal cyst formation." (PMID 31138895, 2019). "Dietary soy protein has been particularly effective in several spontaneous rodent models of renal cystic diseases such as the Han:SPRD-Cy rat with the mutated Anks6 (formally called Pkdr1) gene and the pcy/pcy (pcy) mouse that harbors the pcy mutation." (PMID 27213553, 2016). "Mutations in Ankyrin repeat and sterile alpha motif domain containing 6 (ANKS6) play a causative role in renal cyst formation in the PKD/Mhm(cy/+) rat model of polycystic kidney disease and in nephronophthisis in humans." (PMID 26327442, 2015). "The R823W mutation associated with cystic kidney disease causes a destabilization of the ANKS6 SAM domain which disrupts binding to ANKS3." (PMID 24998259, 2014). "Notably, mutations in ANKS6 have also been found in humans, leading to cystic kidney disease." (PMID 38397964, 2024). "This study presents the important contribution of ANKS6 in early-onset cystic kidney disease and infantile NPHP as well as other multisystem features consistent with its role in the primary cilium." (PMID 39596574, 2024). "Cys1, Nphp3, Anks6 (also called Pkdr1/Nphp16), and Pkhd1 have since been identified as responsible for the development of renal cysts in murine strains in the cpk mouse, pcy mouse, Han:SPRD-Cy/+ rat (commonly known as the Cy rat), and PCK rat, respectively." (PMID 36675597, 2023). "Bicc1 and the ankyrin and SAM domain proteins ANKS3 and ANKS6 all suppress renal cysts and can coprecipitate each other." (PMID 29995892, 2018). "A class of bioactive lipid metabolites called cyclooxygenase (COX) oxylipins (e.g., prostaglandins, leukotrienes) has been shown to be elevated in diseased kidneys of rodent models of NPH (pcy/Nphp3 and jck/Nek8/Nphp9 mice and Han:SPRD-Cy/Anks6/Nphp16 rats) and other cystic kidney diseases." (PMID 34055783, 2021). "A network of protein partners of ANKS6 is emerging and their functional characterization provides important clues to understand the role of ANKS6 in renal biology and in mechanisms involved in the formation of renal cysts." (PMID 26327442, 2015). "In spite of the important role of the ANKS6-SAM domain in cystic kidney disease, the function of ANKS6 remains unknown." (PMID 24998259, 2014). "The emergence of a protein network involving ANKS6, ANKS3 and BICC1 provides important clues on novel mechanisms involved in the formation of renal cysts." (PMID 26327442, 2015).
cystic kidneys (7 papers, 2015 to 2023). "More recently, Bicc1 was identified as a binding partner of the ankyrin repeat- and SAM domain-containing protein ANKS6, which is mutated in cystic kidneys of a subset of nephronophthisis patients." (PMID 29995892, 2018). "Mouse models of InvsC defects (Invs, pcy/Nphp3, jck/Nek8/Nphp9 and Anks6/Nphp16-mutated mice) show enlarged cystic kidneys characteristic of infantile NPH, although pcy/Nphp3 and Anks6/Nphp16 mice have slow disease progression and (late stage) tubulointerstitial fibrosis." (PMID 34055783, 2021). "This is in agreement with the phenotype of Anks6Streaker mice whose Anks6 mutation (p.M187K) decreases the binding to and activation of Nek8 and leads to cystic kidneys, situs inversus and congenital heart defects, thus mimicking the phenotype of patients with NEK8 mutations." (PMID 26967905, 2016). "Moreover, a chemically induced point mutation in the SAM domain of ANKS6 that impairs its recruitment to Bicc1 in cystic kidneys of ANKS6I747N/I747N mice has been shown to diminish the accumulation of polycystin-2, a phenotype that is reminiscent of Bicc1 loss-of-function." (PMID 37733651, 2023). "Indeed, mutations in genes encoding other components of the INVS compartment (INVS/NPHP2, NPHP3 and ANKS6/NPHP16) are known to lead to infantile NPH associated with enlarged cystic kidneys or to kidney cystic dysplasia associated with congenital heart defects and situs inversus." (PMID 26967905, 2016). "Interestingly, we also identified a homozygous frameshift mutation (c.1010_1011del, p.G337Afs*16, family 6) in ANKS6 in a fetus whose phenotype was similar to that of NEK8 loss of function cases, i.e. enlarged cystic kidneys associated with enlarged fibrotic pancreas, situs inversus and cardiopathy." (PMID 26967905, 2016). "The function of this compartment is poorly understood, but human or mouse mutations in genes encoding components of the INVS compartment, INVS/NPHP2, NPHP3 and ANKS6/NPHP16, are known to lead to infantile nephronophthisis with cystic kidneys, congenital heart defects and laterality defects." (PMID 26967905, 2016).
nephronophthisis (7 papers, 2014 to 2024). Progressive tubulointerstitial injury, inherited in an autosomal recessive pattern, caused by mutations in genes involved in ciliary function, which may result in an end stage renal failure. "Han:SPRD rats are not a homologous model of human ADPKD having a missense mutation in Anks6 gene, which causes Nephronophthisis (NPHP)‐like renal pathology in humans." (PMID 36946001, 2023). "ANKS6 mutations are known to cause nephronophthisis 16 (NPHP-16)." (PMID 39596574, 2024). "Mutations in ANKS6 are known to cause a nephronophthisis-like phenotype." (PMID 33240314, 2020). "Moreover, 8 individuals from 6 different families bearing homozygous mutations in ANKS6 all presented with nephronophthisis, which is essentially an infantile or juvenile onset of PKD." (PMID 24998259, 2014). "Our data add NME3 and ANKS6 to the number of proteins linked to both ciliopathies and the DNA-damage response and thus strengthen substantially the notion that replication stress and the genomic instability of tubule cells may contribute to the pathogenesis of nephronophthisis." (PMID 30111592, 2018). "We report initial characterization of the molecular consequences of in vivo renal downregulated expression of mouse ANKS3, a structurally related protein partner of ANKS6 involved in renal cystogenesis in mice and rats and nephronophthisis in humans." (PMID 26327442, 2015). "More recently, localisation of ANKS6 to the primary cilium and interactions between ANKS6 and proteins involved in nephronophthisis (INVS, NHPH3, NEK8) were demonstrated." (PMID 26327442, 2015). "Genetic studies and cohort analyses have identified ANKS6 mutations in patients with nephronophthisis, but no specific geographical prevalence has been established." (PMID 39596574, 2024).
polycystic kidney (5 papers, 2014 to 2024). "Here, we report the detection of ANKS6 variants in consanguineous families with polycystic kidney antenatally and in the early stages of life." (PMID 39596574, 2024). "The recent finding of mutations in ANKS6 in individuals presenting with polycystic kidney disease has catapulted this protein from relevance in an animal model to having direct implications for human renal development and function." (PMID 24998259, 2014). "The same limitations are found in the Lewis polycystic kidney (LPK), Wistar polycystic kidney (Wpk) and Cy rat models, with mutations in the orthologs of human NEK8/NPHP9, TMEM67/NPHP11 and ANKS6/NPHP16 genes, respectively." (PMID 34055783, 2021). "Though the precise role of ANKS6 in renal cystogenesis is not fully understood, a recent study provides a compelling argument for the potential role of ANKS6 and NEK8 in regulating polycystic kidney function." (PMID 38397964, 2024).
cyst (3 papers, 2021 to 2024). A sac-like closed membranous structure that may be empty or contain fluid or amorphous material. "The Han:SPRD rat model, carrying an R823W mutation in the Anks6 gene, is characterized by cyst formation and kidney enlargement." (PMID 38397964, 2024). "Treatment of Han:SPRD-Cy/Anks6/Nphp16 rats with the anti-inflammatory drug resveratrol attenuated cyst formation, elevated serum creatinine and macrophage infiltration partly through inhibition of mTOR signaling and the NF-kB pathway." (PMID 34055783, 2021). "Interestingly, levels of both COX2 and PGE2 are increased in PKD models and patient cyst fluid, and inhibition of COX2 has been shown to ameliorate PKD in Anks6+/– (Han:SPRD Cy/+) rats, a nonorthologous ADPKD model, and in Pkd2WS25/− mice." (PMID 36422996, 2023).
aortic stenosis (2 papers, 2014 to 2024). Aortic valve stenosis is a aortic valve disease caused by the incomplete opening of the aortic valve. "In the heart, the splice-site and truncating mutations of ANKS6 were linked to hypertrophic obstructive cardiomyopathy, aortic stenosis, pulmonary stenosis, patent ductus arteriosus, and situs inversus." (PMID 38397964, 2024). "Furthermore, the fact that one patient with a truncation in ANKS6 at the N-terminal end of the SAM domain also presented with aortic stenosis, causing obstructive cardiomyopathy, implicates ANKS6 in cardiac development and function." (PMID 24998259, 2014). "The involvement of ANKS6 in cardiac development and function is further supported by the observation that a patient who had a truncation in ANKS6 at the N-terminal end of the SAM domain, who also presented aortic stenosis, resulted in obstructive cardiomyopathy." (PMID 38397964, 2024).
autosomal recessive polycystic kidney disease (1 paper, 2014). An inherited disorder characterized by the development of cysts affecting the collecting ducts. "ANKS6 has been linked to Bicaudal-C1 (BICC1), a protein that when mutated is responsible for disease in the jcpk mouse model of ADPKD and the bpk mouse model of ARPKD (autosomal recessive polycystic kidney disease)." (PMID 24998259, 2014).
breast carcinoma (1 paper, 2020). "Based on Cancer Genetic Markers of Susceptibility breast cancer study (CGEMS), 3 SNPs located between ANKS6 and GALNT12 were identified as significantly associated with breast cancer." (PMID 33240314, 2020).
collagenopathies (1 paper, 2024). "Genetic findings that modified the diagnosis in 19 patients included mutations in patients with NPHP (NPHP1 [n = 4], TTC21B [n = 3], ANKS6 [n = 1], NPHP3 [n = 1], NPHP4 [n = 1]), collagenopathies (COL4A5 [n = 7], COL4A3 [n = 1]), and Fabry disease (GLA [n = 1])." (PMID 39363361, 2024).
end-stage renal disease (1 paper, 2024). "The homozygous Anks6 mutation leads to end-stage renal disease and death, making it a critical factor in kidney development and function." (PMID 38397964, 2024).
Kidney Cyst (1 paper, 2023). Abnormal fluid filled sac within the kidney, either acquired or congenital. "In mouse, Anks6, Invs, Nphp3, and Nek8 mutants develop kidney cysts, while mutants of several other NPHP genes show no obvious kidney phenotypes." (PMID 36920028, 2023).
kidney disease (3 papers, 2024). "Little is known regarding fetal ultrasound imaging and the antenatal diagnosis of fetuses with ANKS6-associated kidney disease." (PMID 39596574, 2024). "Recent findings have established an association between ANKS6 and human kidney disease, particularly with nephronophthisis." (PMID 38397964, 2024). "These cases provide examples in order to understand the complete disease phenotypic spectrum of ANKS6-associated kidney disease." (PMID 39596574, 2024).
tumor (1 paper, 2024). "We found that the expression of NPHP3, DVL1, and DVL3 was significantly higher and the expression of ANKS6 was significantly lower in the primary tumor in comparison to the normal solid tissue." (PMID 39596188, 2024). "The expression of DVL3 was positively related and the expression of ANKS6 was negatively related to the tumor’s histological grade." (PMID 39596188, 2024). "We assessed the correlation of INVS and genes of interest in its interactome (NPHP3, DVL1, DVL3, and ANKS6) with tumor immune infiltration and expression using different algorithms (XCELL, TIMER, QUANTISEQ, EPIC, CIBERSORT, CIBERSORT-ABS, and MCPCOUNTER) by using GEPIA." (PMID 39596188, 2024). "Similar results were also found for ANKS6; on the other hand, the expression of DVL3 was positively related with tumor’s histological grade, being the highest in grade 4 and the lowest in grade 1 ccRCC." (PMID 39596188, 2024).
ANKS6 also shares sentences with these, for which no sentence is quoted: cancer (1 paper); ciliopathies (1); Fabry disease (1); infection (1); kidney failure (1); liver cysts (1); melanoma (1); nephronophthisis 16 (1); Periportal fibrosis (1); situs inversus (1).